INS (insulin)
Diseases named in the same sentence as INS in open-access papers (continued):
Sharing a sentence is not in itself a finding about the gene and the disease.
gastric cancer (60 papers, 2009 to 2025). A primary or metastatic malignant neoplasm involving the stomach. "The causal relationships between T2DM with esophageal and gastric cancer are partially mediated by decreased fasting insulin and increased glycated hemoglobin levels, respectively." (PMID 38947888, 2024). "A previous nested case–control study showed a positive association between insulin and C-peptide levels and gastric cancer." (PMID 37455285, 2023). "Firstly, the long-term use of insulin to treat diabetic patients has been linked to an increase in body weight and abdominal fat deposit, which are both associated with an increased risk of stomach cancer according to a meta-analysis of cohort studies." (PMID 39301314, 2024). "There is a positive association between plasma insulin levels and gastric cancer incidence." (PMID 34554347, 2022). "In addition, a large follow-up cohort study showed that the use of insulin and glinides was associated with a higher risk of stomach cancer." (PMID 29082856, 2017). "Our previous studies may provide some insights for the explanation of the association between insulin use and gastric cancer risk observed in the Korean study." (PMID 27587088, 2016). "The result implicated that insulin may cause the change of P-glycoprotein to impact the proliferation and chemosensitivity of gastric cancer cells." (PMID 26084465, 2015). "Finally, some glucose‐lowering therapies, such as sulfonylureas and insulin therapy, may increase gastric cancer risk by interacting with insulin and insulin IGF‐1R signaling." (PMID 38751364, 2024). "Humanized insulin/Gastrin (INS-GAS) transgenic mice are frequently used to model stomach cancer as they have high circulating levels of pancreatic gastrin." (PMID 40438238, 2025). "In this study, we examine Smox-deficiency in an established gastric cancer mouse model, FVB/N insulin-gastrin (INS-GAS) mice, mediated by H. pylori infection." (PMID 39523394, 2025). "Male and female transgenic FVB/N insulin-gastrin (INS-GAS) mice as a model of gastric cancer were randomly administered Brucella Broth or Helicobacter pylori (H. pylori)." (PMID 39985099, 2025). "In this study, we demonstrate that transgenic FVB/N insulin-gastrin (INS-GAS) mice that develop gastric carcinoma with H. pylori infection were protected from cancer development with Smox deletion." (PMID 39523394, 2025). "Insulin metabolism parameters were also investigated regarding their relationship to gastric cancer." (PMID 38255710, 2024). "Insulin-gastrin-secreting (INS-GAS) mice are genetically susceptible to GC and are therefore commonly used in developing mouse gastric cancer models." (PMID 37583514, 2023). "Despite the lack of epidemiological data, a recent in vitro study demonstrated that insulin exhibits direct cancer-promoting effects on gastric cancer cells." (PMID 37455285, 2023). "Epidemiological studies indicate that insulin promotes higher rates of gastric cancer presentation and mortality." (PMID 34554347, 2022). "The most powerful evidence proving the role of LAB in gastric cancer development was obtained from an insulin-gastrin (INS-GAS) transgenic mouse model." (PMID 35606878, 2022). "To further demonstrate the role of Akt/mTOR dephosphorylation in narciclasine-induced autophagy, we treated gastric cancer cells with insulin (Akt activator) to reactivate Akt/mTOR signaling pathway." (PMID 34753517, 2021). "On the contrary, insulin was found to confer anti-apoptotic effect on gastric cancer cell lines treated with 5-FU." (PMID 34034636, 2021). "Higher gastric cancer risk was found in the group of diabetic patients treated with sulfonylureas (SIR 1.31, 95% CI: 1.04–1.65) as well as insulin and other medications (SIR 1.16, 95% CI: 0.73–1.84), although the latter result was insignificant." (PMID 32033451, 2020).
gastric cancer (continued). "In conclusion, the present study identified that expressions of miR-20b and miR-451a are significantly deregulated in gastric cancer tissue, commercial cell cultures, and INS-GAS mice." (PMID 32013265, 2020). "Animal studies showed that gastric cancer developed in 37% (10/27) of Mongolian gerbils 62 weeks after inoculation of H. pylori and in 75% (6/8) of insulin-gastrin (INS-GAS) transgenic mice after inoculation of H. felis." (PMID 31035365, 2019). "Gastric cancer was successfully induced in Mongolian gerbils and insulin-gastrin (INS-GAS) transgenic mice after inoculation of H. pylori." (PMID 31035365, 2019). "Two studies demonstrated that complex gastric microbiota can promote H. pylori-induced gastric cancer by hastening the onset of malignancy and promoting tumor progression using hypergastrinemic insulin-gastrin (INS-GAS) transgenic mouse model." (PMID 30619779, 2018). "The few studies that have examined gene expression profiles in mouse model of gastric cancer have used the insulin-gastrin (INS-GAS) transgenic gastric cancer mouse model." (PMID 28201999, 2017). "With the development and improvement of gene transfer technology, investigators created a variety of transgenic and knockout/knockin mouse models of gastric cancer, such as INS-GAS mice and gastrin knockout mice." (PMID 27713138, 2017). "In the transgenic insulin-gastrin (INS-GAS) mouse model of spontaneous gastric cancer, H. pylori drove disease progression and the development of intraepithelial neoplasia." (PMID 27688750, 2016). "In our experiment, we found that the proliferation of different gastric cancer cell lines was remarkably accelerated by high level of insulin compared with controlled GES cells." (PMID 26084465, 2015). "Insulin improved the proliferation of gastric cancer cell lines and contributed to chemoresistance of gastric cancer cells to 5-fluorouracil which is likely to involve upregulation of P-glycoprotein." (PMID 26084465, 2015). "In our study, we try to explore the direct influence of insulin on the chemotherapeutic sensitivity of three gastric cancer cell lines to 5-fluorouracil." (PMID 26084465, 2015). "This study aimed to explore the impact of insulin on chemoresistance to 5-fluorouracil in gastric cancer and the possible mechanisms." (PMID 26084465, 2015). "In our study, we also found that the insulin-induced drug resistance to 5-fluorouracil correlated with the augment of P-glycoprotein in gastric cancer." (PMID 26084465, 2015). "When added 5-fluorouracil, the three gastric cancer cell lines showed decreased chemotherapeutic responses when simultaneously administered insulin while the cell viability." (PMID 26084465, 2015). "The effect of insulin on chemotherapeutic sensitivity of the three gastric cancer cell lines to 5-fluorouracil was evaluated by pre-incubation with insulin before administration of 5-fluorouracil." (PMID 26084465, 2015). "However, after TG for gastric cancer, not only is the body weight and PV reduced, but the insulin secretion and pancreatic exocrine function are also decreased." (PMID 37084095, 2023). "Triglyceride synthesis is stimulated by insulin; So it is concluded that the etiology of CL after gastric cancer surgery may be related to two variables, namely, triglycerides and insulin." (PMID 36176409, 2022). "Tumour promotion activities of insulin and its receptor are untested in gastric cancer cells." (PMID 34554347, 2022). "Moreover, its effector protein RAB3IP is involved in insulin exocytosis from pancreatic β cells and promotes cell proliferation via inhibiting autophagy in gastric cancer." (PMID 32759795, 2020). "Like us, other researchers have assessed the effect of different antihyperglycemic medications (insulin, metformin, sulfonylureas, thiazolidinediones, alpha-glucosidase inhibitors, non-sulfonylurea insulin secretory analogues) on gastric cancer risk." (PMID 32033451, 2020).
gastric cancer (continued). "Neither metformin nor sulfonylureas had any effect on gastric cancer risk (insulin vs. metformin (OR), 1.855; 95% CI: 0.779–4.419 and sulfonylurea vs. metformin (OR), 1.547; 95% CI: 0.923–2.594)." (PMID 32033451, 2020). "A randomized controlled single-center parallel study involving 212 type 2 diabetic patients who had undergone gastrectomy for gastric cancer compared protocol-driven intravenous insulin therapy with conventional subcutaneous sliding scale insulin delivery over 8–10 days of continuous EN." (PMID 31261760, 2019). "A recent nested case-control study in Japan found that higher insulin and C-peptide levels elevated risk of gastric cancer in men but not in women." (PMID 30740588, 2018). "The lack of an increased risk of gastric cancer associated with insulin use observed in the present study was also supported by an earlier study conducted in the Taiwanese patients with T2DM." (PMID 27587088, 2016). "We found that insulin could significantly promote the proliferation of gastric cancer cells compared with control mucosa cells." (PMID 26084465, 2015). "In addition, by exploiting genetic engineering, a variety of transgenic and knockout mouse models of gastric cancer have emerged, such as INS-GAS mice and TFF1 knockout mice." (PMID 24216700, 2013). "For example, ciRS-7 indirectly up-regulates the expressions of miR-7 target genes by binding to miR-7 and therefore participating in processes such as insulin secretion, myocardial infarction and gastric cancer (GC) progression." (PMID 36386850, 2022). "Treating male patients with T2DM who do not use insulin for H. pylori treatment may be promising in reducing the risk of gastric cancer." (PMID 29082856, 2017). "It is worthy to note that in the Korean study, gastric cancer risk might be doubled in insulin users while compared to nonuser, disregarding metformin use." (PMID 27587088, 2016). "Finally, using a tumor xenograft model, we proposed that HIF-1α inhibition combined with glucose plus insulin (GI) treatment may be a potential therapy for gastric cancer." (PMID 26339797, 2015). "Since results above showed that high level of insulin promoted gastric cancer cells growth and 5-fluorouracil was therapeutically effective to gastric cancer cells, we then examined whether high insulin induced chemoresistance to 5-fluorouracil in gastric cancer cells." (PMID 26084465, 2015). "Further, insulin and type I IGF receptors mediated lapatinib resistance of HER2-amplified SNU-216 gastric cancer cells." (PMID 34554347, 2022). "In addition, our results revealed that the apoptosis rate of gastric cancer cells in the narciclasine combined with the insulin group was lower than that in the narciclasine group, and insulin could reduce the effects of narciclasine on inhibiting the proliferation of gastric cancer cells." (PMID 34753517, 2021). "Although an important population-based study compared the incidence of gastric cancer in insulin users and nonusers and showed a lack of association between insulin use and gastric cancer, which might due to DM patients received insulin or not with different DM status." (PMID 28415651, 2017). "The HR for stomach cancer among patients taking GLP-1RAs vs those taking insulin was less than 1, but it was not statistically significant (HR, 0.73; 95% CI, 0.51-1.03)." (PMID 38967919, 2024). "Although not statistically significant, the HR for stomach cancer was less than 1 among patients who took GLP-1RAs compared with those who took insulin (HR, 0.73; 95% CI, 0.51-1.03)." (PMID 38967919, 2024). "On the other hand, a Korean study demonstrated a reduced risk of gastric cancer in patients with T2DM who had been using metformin for >3 years and not being treated with insulin (adjusted HR 0.57, 95% CI: 0.37-0.87)." (PMID 27587088, 2016). "Actually, HP infection significantly increased the risk of gastric cancer (Model VIII) but insulin did not much affect the risk of gastric cancer (Model I) in the present study." (PMID 27587088, 2016).
gastric cancer (continued). "In vitro study of gastric cancer cell lines also showed higher P-glycoprotein under the condition of insulin, especially high insulin, than without insulin in treatment of 5-fluorouracil." (PMID 26084465, 2015). "In the presence of 1 μM of insulin, the toxic effect of 5-fluorouracil on gastric cancer cells was apparently compromised and cell number was much more after treatment than with low concentration of insulin or without insulin." (PMID 26084465, 2015). "Gastric cancer cells and controlled cells were treated with different concentrations of 5-fluorouracil without addition of insulin." (PMID 26084465, 2015). "With the presence of insulin, the level of P-glycoprotein was highly upregulated in gastric cancer cells in contrast to the nonobvious alteration in GES cells." (PMID 26084465, 2015). "We used Western-blot analyses to investigate the expression of P-glycoprotein in different gastric cancer cell lines with or without administration of insulin and 5-fluorouracil." (PMID 26084465, 2015). "However, in contrast to the hypergastrinemic INS-GAS mice which developed corpus cancers, GAS−/− mice exhibited antral gastric cancers." (PMID 24216700, 2013). "Insulin, insulin-like growth factor 1(IGF1) and insulin-like growth factor 2(IGF2) were the most studied insulin-like peptides (ILPs) regarded as key regulators of energy metabolism and growth, especially IGF1 receptor and IGF2 receptor were expressed in gastric carcinoma cells." (PMID 30299268, 2018). "We do not attempt to elucidate the detailed mechanisms of insulin-induced drug resistance but to provide an in vitro clue which may be beneficial for further research on gastric cancer and clinical treatment." (PMID 26084465, 2015). "The improvement of prognosis in gastric cancer patients with positive AdipoR1 expression might be affected by organ protective effects from insulin resistance and inflammatory states rather than as a result of a direct antiproliferative effect via globular adiponectin." (PMID 22078265, 2011).
neuroblastoma (60 papers, 2006 to 2025). Neuroblastoma (NB) is the most common solid, extracranial childhood tumor. "In neuroblastoma cells, excessive ROS generated by NOXs after insulin stimulation causes oxidative inactivation of PTEN and phosphorylation activation of PI3K/AKT." (PMID 33754031, 2021). "Activation of insulin signalling activation may also be implicated in the promotion of mTOR-independent autophagic clearance of poly(Q) aggregates in N2a mouse neuroblastoma cells." (PMID 33739284, 2021). "This implicated that APN could also enhance insulin sensitivity in Aβ-overproducing neuroblastoma cells." (PMID 27884163, 2016). "Insm2 was shown to regulate insulin secretion in mice and lipid metabolism in neuroblastoma cell lines." (PMID 40362725, 2025). "In cortical neurons and differentiated human neuroblastoma cells, the PA-dependent reduction in insulin signaling activates the nutrient-sensing kinase mTOR complex C1 and increases intracellular Ca2+ levels, which in turn, activate protein kinase C⍺ (PKC⍺)." (PMID 40208460, 2025). "A similar effect was observed in differentiated human neuroblastoma cells, in which treatment with PA for 1 h generated sustained ROS production that inhibited insulin signalling and insulin‐dependent mitochondrial activation." (PMID 36321333, 2023). "In the neuroblastoma cell line, the E2F-targeted portions of cancer pathways, thermogenesis, mTOR signaling, insulin signaling, and circadian entrainment were all inhibited, as one would expect based on the previous research on E2F1." (PMID 36271102, 2022). "The lead compound furthermore partially prevented Aβ-induced cell death in a neuroblastoma cell line, as did high dose insulin and pioglitazone treatments." (PMID 35061720, 2022). "Kim described the neuroprotective role of insulin in 1-Methyl-4-phenyl pyridinium (MPP+)-induced toxicity in retinoic acid-differentiated human neuroblastoma SH-SY5Y cells." (PMID 35454152, 2022). "In our previous experiments we studied the effect of STZ on insulin sensitivity of undifferentiated SH-SY5Y neuroblastoma cells." (PMID 33616807, 2021). "To investigate the relationship between APP O-GlcNAcylation and APP endocytosis, we tested the effects of insulin on neuroblastoma SH-SY5Y cells overexpressing APP and BACE1, and cultured rat hippocampal neurons." (PMID 34940409, 2021). "In our previous in vitro study, we examined how insulin sensitivity of the undifferentiated SH-SY5Y neuroblastoma cells is influenced by STZ treatment." (PMID 33616807, 2021). "Briefly, SHSY-5Y neuroblastoma cells were pretreated for 24 h with a mixture of insulin and palmitic acid (IPA) in order to reproduce the metabolic changes observed in HFD mice hippocampi." (PMID 33916835, 2021). "There is a specific binding site for insulin in the neural crest origin, which suggests a correlation between insulin and neurite formation in human neuroblastoma SH‐SY5Y cells." (PMID 32281722, 2020). "It has also been shown that long-term application of insulin modifies the expression of the TRPV1 receptor protein in neuroblastoma cells by regulating the PI3K and MAPK signaling." (PMID 32260335, 2020). "The same treatment was equally found to induce Aβ degradation in a mouse neuroblastoma cell line (N2a) through inhibiting the insulin-degrading enzyme." (PMID 32085610, 2020). "Further, it has also been demonstrated that insulin promotes the neurite outgrowth of human neuroblastoma cells as well." (PMID 32260335, 2020). "We also observed CLASP2 relocalization to MT plus-ends upon insulin or IGF-1 treatment in neuroblastoma cells or neurons, respectively." (PMID 30787869, 2019). "We further validated our findings in vitro in human neuroblastoma cells under insulin resistant conditions." (PMID 31427921, 2019).